RNU6-780P (RNA, U6 small nuclear 780, pseudogene)
Gene: Small nuclear RNA gene on chromosome 10 (86,488,446 to 86,488,549, forward strand). Ensembl gene ENSG00000212332.
Homologues: Orthologues: chimpanzee U6 (100% identical), macaque U6 (93% identical). Paralogues in human: RNU6-11P (85% identical), RNU6-37P (85% identical), RNU6-7 (85% identical), RNU6-8 (85% identical), RNU6-1 (84% identical), RNU6-2 (84% identical), RNU6-3P (84% identical), RNU6-4P (84% identical), RNU6-5P (84% identical), RNU6-6P (84% identical), RNU6-9 (84% identical), RNU6-12P (83% identical), and 1283 more.